NLRP3 (NLR family pyrin domain containing 3)
Diseases named in the same sentence as NLRP3 in open-access papers (continued):
Sharing a sentence is not in itself a finding about the gene and the disease.
depression (continued). "The inflammasome hypothesis of depression states that psychological stress activates NLRP3 and proposes the pathway between NLRP3 to IL1β as an underlying mechanism of MDD." (PMID 35002816, 2021). "Further, ASC mRNA and protein were altered in CD36−/− mice, indicating that ASC may be required for CD36-mediated regulation of NLRP3 activation and depression." (PMID 33414380, 2021). "Therefore, NLRP3 has very important clinical value in the screening, early recognition and treatment of depression." (PMID 34526897, 2021). "In addition, NLRP3 inflammasome is activated in mononuclear blood cells of patients with major depressive disorder." (PMID 33609086, 2021). "Herein, we hypothesized that Ori may inhibit NLRP3 inflammasome activation by promoting autophagy, thereby having the function of alleviating depression." (PMID 35096901, 2021). "The astrocytic NLRP3 KO results reported here suggest that astrocytic NLRP3 inflammasome had a significant effect on the astrocytic pyroptosis via the downstream Casp-1/GSDMD pathway in the pathophysiology of depression." (PMID 34877938, 2021). "α-Cyperone was reported to exert antidepressant-like actions in a mice depression model which may be attributed to suppressing NLR family pyrin domain containing 3 (NLRP3) inflammasome." (PMID 34925022, 2021). "Hence, Ori administration significantly decreased NLRP3 inflammasome activation via autophagy activation in the hippocampus of LPS-induced depression mouse models." (PMID 35096901, 2021). "Additionally, chronic swimming exercise and voluntary wheel exercise also inhibited the NLRP3 inflammasome overactivation due to depression, high-fat diet, and chronic kidney disease." (PMID 34639204, 2021). "The study of lipopolysaccharide induced depression-like behavior in mice found that NLRP3 inflammasomes inhibitor could block depressive behavior in mice." (PMID 34531719, 2021). "Based on these discoveries, the inhibition of NLRP3 inflammasome activity and inflammatory substances downstream may provide an avenue to develop new treatments for depression." (PMID 33609086, 2021). "The first evidence that the NLRP3 inflammasome might be involved in the pathogenesis of depression came from behavioral studies in a mouse model of lipopolysaccharide-induced depression." (PMID 34526897, 2021). "Significant changes in NLRP3 were found in both central and peripheral studies of animal depression models, suggesting that NLRP3 inflammasomes may be an important target for depression treatment." (PMID 34526897, 2021). "Besides, the activation of NLRP3 inflammasome assembly was reported to be capable to induce the depression-like behaviors of mice by LPS injection or chronic unpredictable mild stress (CUMS) stimulation." (PMID 34877938, 2021). "Significant changes in NLRP3 have been found in the central and peripheral studies of animal depression models, and it is speculated that NLRP3 inflammasome may be an important target for the treatment of depression." (PMID 34526897, 2021). "The NLRP3-mediated pyroptosis, which could be regulated by miRNA-27a, is a key player in the development of depression." (PMID 33402173, 2021). "There have been a few studies highlighting the role of NLRP3 inflammasome in depression." (PMID 33329109, 2020). "Recent studies show that the nod-like receptor family pyrin domain containing 3 (NLRP3) inflammasome is upregulated in microglia and may play an important role in depression." (PMID 32414166, 2020). "We hypothesize that TCA may treat depression via inhibiting the activation of NLRP3 inflammasome and NF-κB pathway." (PMID 32328132, 2020). "The correlation between NLRP3 inflammasome and depression has also been documented." (PMID 33132912, 2020). "Therefore, chronic antidepressant treatment can attenuate depression-like disturbances in the hippocampus by inhibiting the activation of NLRP3 inflammasomes." (PMID 32166013, 2020).
depression (continued). "Moreover, studies show NLRP3 inflammasome activation in animal models of depression as well as in patients with depression." (PMID 32414166, 2020). "A study on the relationship between gut microbiota and depression showed that the depressive-like behavior of recipient mice induced by chronic unpredictable stress can be significantly alleviated by transplanting an NLRP3 knockout microbiota." (PMID 32166013, 2020). "Our results are in consistent with animal models of depression with NLRP3 inflammasome activation." (PMID 32410849, 2020). "Recent evidence also suggests that NLRP3 is a common mediator in the development of depression." (PMID 31439031, 2019). "Indeed, NLRP3 gene expression was found elevated in PBMCs of patients with major depression corresponding with elevated serum levels of IL-1β and IL-18, supporting the clinical applicability of inflammasome activation in depression." (PMID 31749681, 2019). "Inhibiting glucocorticoid release, NF-κB nuclear transcription, NLRP3 inflammasome activation and restoring microglial homeostasis in the hippocampus are novel strategies for the development of effective treatments for the management of depression in humans." (PMID 31555091, 2019). "An important question that arises is whether drugs currently used in the pharmacotherapy of depression exhibit anti-inflammatory potential, particularly in brain immune cells, via an impact on NLRP3 inflammasome-related pathways." (PMID 30610610, 2019). "Accumulating evidence indicates that the NLRP3 inflammasome is involved in neuroinflammation, neurodegenerative disorders and neuropsychiatric disorders such as depression." (PMID 31555091, 2019). "The NLRP3 inflammasome activation links cytokines, psychological stress, and depression." (PMID 30610610, 2019). "Our study illustrates the involvement of the gut microbiota-circHIPK2-astrocyte axis in depression, providing translational evidence that transplantation of the gut microbiota from NLRP3 KO mice may serve as a novel therapeutic strategy for depression." (PMID 31439031, 2019). "In the present study, we showed that melatonin ameliorated LPS-induced behavior abnormalities in a mouse model of acute systemic inflammation and depression, and decreased NLRP3 inflammasome activation in mice hippocampi as evidenced by qPCR, Western blot and immunofluorescence staining." (PMID 31327964, 2019). "Moreover, it has been reported that NLRP3 signaling plays a key role in microglial activation and inflammation in LPS-induced depression." (PMID 31736656, 2019). "NLRP3 has been found to be activated in depression patients and rodent models of depression." (PMID 31439031, 2019). "Recent studies show that the Nod-like receptor protein 3 (NLRP3) inflammasome is expressed in microglia and may play a crucial role in depression." (PMID 31555091, 2019). "In addition, IL-1β, whose secretion is tightly controlled by the NLRP3 inflammasome, plays a critical role in the pathogenesis of depression." (PMID 31555091, 2019). "In our study, we only focus on the role of NLRP3 in the process of depression." (PMID 31555091, 2019). "Recent studies demonstrated that inhibiting the hippocampal NLRP3 inflammasome activation could ameliorate cognitive dysfunction and depression in mice." (PMID 29495433, 2018). "Another CNS disease highly related to the NLRP3 inflammasome is depression." (PMID 30233319, 2018). "In addition, other agents targeting on the inhibition of the NLRP3 inflammasome were reported in animal depression models, although the specific mechanisms remained unclear." (PMID 30233319, 2018). "The NLRP3 inflammasome may be a central mediator between immune activation and development of depression." (PMID 29343269, 2018).
depression (continued). "Two recent studies have shown further evidence that antidepressant drugs can modulate central NLRP3 inflammasome activation, microglial structure and function, thereby suggesting the therapeutic potential of targeting neuroinflammation to treat depression." (PMID 29946236, 2018). "Moreover, Gas ameliorates cognitive dysfunction and depression-like behaviors of db/db mice by inhibiting ER stress and NLRP3 inflammasome activation." (PMID 30544722, 2018). "Inhibition of hippocampal NLRP3 inflammasome activation by MCC950—a small-molecule inhibitor of the NLRP3 inflammasome—improved cognitive dysfunction as well as anxiety- and depression-like behaviors in db/db mice, thus offering an effective potential therapeutic approach for DEP treatment." (PMID 29495433, 2018). "Importantly, some drugs conferred an antidepressant effect in a model of depression by inhibiting NLRP3 inflammasome activation." (PMID 28533742, 2017). "Based on these clues, it is reasonable to hypothesize that the interrelationship between autophagy and neuroinflammation process, especially NLRP3 activation, may play a pivotal role in the progression of depression." (PMID 29212498, 2017). "Overall, these findings indicate that the NLRP3 inflammasome is involved in the pathogenesis of depression and CLD, understanding its role in both diseases may build a linkage between them." (PMID 28533742, 2017). "NLRP3 inflammasomes could play a major role in the comorbidity of depression with other systemic diseases, indirectly through an inflammatory response in the brain." (PMID 28943841, 2017). "The NLRP3 inflammasome activation and neuroinflammation are known to be involved in the pathology of depression, whereas autophagy has multiple effects on immunity, which is partly mediated by the regulation of inflammasome and clearance of proinflammatory cytokines." (PMID 29212498, 2017). "The NLRP3 inflammasome may also play a role in the onset of depression through the gut-brain axis." (PMID 41194915, 2025). "In addition, chronic ethanol exposure (CEE) induces gut microbiota dysbiosis and impairs gut homeostasis, resulting in elevated circulating LPS and inflammatory cytokines that activate hippocampal NLRP3 inflammasomes, resulting in neuroinflammation and depression-like symptoms." (PMID 40936908, 2025). "In addition, retinal injury may initiate hippocampal microglial activation via the NLRP3/IL-1β pathway, leading to neuroinflammation and subsequent depression-like behavior." (PMID 40936908, 2025). "Additionally, we discovered that VTX, an antidepressant known for its cognitive benefits in depression, notably counteracts the abnormal NLRP3 inflammasome expression, particularly in the dorsal hippocampus 24 h after LPS exposure, potentially via regulating NEK7 expression." (PMID 39005130, 2025). "Some studies suggest that anti-inflammatory medications could prevent and treat depression by altering the composition and quantity of beneficial gut bacteria, highlighting the potential of targeting gut microbiota and the NLRP3 inflammasome as strategies for preventing PPD." (PMID 41409594, 2025). "Therefore, regulating the NF-κB signaling pathway may be one of the key mechanisms by which the NLRP3 inflammasome mediates the prevention and treatment of depression through exercise." (PMID 40699781, 2025). "Mitochondrial dysfunction leads to the release of mtDNA and increased ROS, activating the STING1 and NLRP3 inflammasome signaling pathways, promoting the synthesis of inflammatory factors, and consequently triggering inflammation that mediates the occurrence of depression." (PMID 40699781, 2025). "In a chronic mild stress (CMS) model of depression characterized by anhedonia, UCP2-deficient mice showed exacerbated depressive behaviors, whereas UCP2 overexpression produced antidepressant effects by suppressing the ROS-thioredoxin-interacting protein (TXNIP)–NLRP3 pathway in astrocytes." (PMID 41441267, 2025).
depression (continued). "It has been shown that IL-1β and IL-18 released upon the activation of NLRP3 inflammatory vesicles may be key molecules in triggering the immune response in depression and further exacerbate the pathological process through Gasdermin D (GSDMD)-mediated cellular pyroptosis response." (PMID 40497971, 2025). "In addition, NLRP3 mediates other signaling pathways relevant to depression." (PMID 40936908, 2025). "Additionally, the abnormal activation of the NLRP3 inflammasome not only affects mood, but may also precipitate other complications related to depression." (PMID 41194915, 2025). "Given the shared involvement of NLRP3 inflammasome in MI and depression pathogenesis, inhibiting its activation could be a promising therapeutic strategy for individuals with comorbid MI and depression." (PMID 38970230, 2024). "TLR4-NF-κB/NLRP3/ IL-1β pathway may be a key signaling pathway in depression." (PMID 38459460, 2024). "Additionally, the activation of the eATP-P2X7R signaling pathway disrupts the structural and functional equilibrium of ER-mitochondria contacts, consequently triggering NLRP3 inflammasomes assembly in microglia and further contributing to the development of depression-like behavior." (PMID 38890305, 2024). "First, it has been discovered that rodent depression models and people with MDD both have active NLRP3 inflammasomes." (PMID 38855751, 2024). "It was found that the level of BDNF protein in the hippocampus was significantly up-regulated, and the levels of NF-κB, NLRP3, and IL-1β were significantly decreased, suggesting that salidroside may ameliorate depression by inhibiting the NF-κB/NLRP3 signaling pathway." (PMID 39770545, 2024). "However, it is unclear whether MT improves microglia pyroptosis by inhibiting the Cathepsin B/NLRP3 pathway, thereby alleviating hippocampal injury and subsequent depression-like behaviors." (PMID 38538614, 2024). "Therefore, targeting NF-κB/NLRP3 through potential anti-inflammatory components may potentially reduce anxiety and depressive disorders." (PMID 38911248, 2024). "Thus, the NLRP3 inflammasome may mediate the effects of drugs that alleviate depression-like behaviors." (PMID 36909192, 2023). "What’s more, depression-like behaviors could be improved by knocking or suppressing the NLRP3 gene." (PMID 37293210, 2023). "That is, NLRP3 inflammatory vesicles may be important in triggering depression." (PMID 37492068, 2023). "Interestingly, NLRP3 inflammasome is the pathogenesis of both chronic liver disease and depression." (PMID 36979246, 2023). "However, clinical data regarding the involvement of NLRP3 in patients with depression are limited." (PMID 37763063, 2023). "Thus, our above findings that H2S pretreatment improves mitochondrial function and the suppression of NLRP3 inflammasome activation indicate that H2S arrests the interplay of mitochondrial dysfunction in the hippocampus of the LPS-induced depression-like model." (PMID 37626978, 2023). "Furthermore, probiotic could improve depression-like behaviors by amending the microbiota and suppressing the activation of NLRP3 inflammasome." (PMID 37293210, 2023). "Furthermore, the inhibition of NLRP3 inflammasome may have the potential to reduce the risk of depression after AMI, particularly within the subgroup exhibiting elevated baseline levels of NLRP3, leading to improvements in cardiovascular outcomes." (PMID 37763063, 2023). "Therefore, the activation of NLRP3 induced by chronic stress may be a potential mechanism of cognitive decline in depression." (PMID 37165444, 2023). "Therefore, probiotics may improve depression by altering the intestinal flora and inhibiting the activation of NLRP3 inflammasomes." (PMID 37293210, 2023). "However, there are few experimental studies that have investigated whether exercise can intervene and regulate the pathological process of depression through the NLRP3 signaling pathway, particularly the SIRT3/ROS/NLRP3 axis." (PMID 37629568, 2023).
depression (continued). "Given that NLRP3 inflammasome may be play a key role in depression." (PMID 37293210, 2023). "Therefore, modulating the NLRP3 signaling pathway and further inhibiting neuroinflammation may be a therapeutic strategy to improve depression." (PMID 36339940, 2022). "Taken together, our results and previous studies confirmed that chronic stress could activate the microglia in the hippocampus, and further the NLRP3 inflammasome expression and activation increased resulting in elevated pro-inflammatory cytokines and ultimately leading to depression." (PMID 35688836, 2022). "NLRP3 may also mediate the regulation of depression by the gut–brain axis." (PMID 35722622, 2022). "Thus, NLRP3 inflammasome plays a crucial role in depression." (PMID 35496273, 2022). "Furthermore, Shugan Hewei Decoction containing Chai Hu (Bupleuri radix), Huang Lian (Coptis chinensis) and Gan Cao (Glycyrrhiza uralensis) has been reported to help manage anxiety and depression in chronic stress model rats by suppressing the NLRP3 inflammasome and cecal microbiota." (PMID 36267291, 2022). "Notably, we found that the NLRP3 expression level was significantly lower in reactive depression patients compared with endogenous depression patients and healthy controls, while the NLRP3 expression levels of healthy controls and endogenous depression patients were not significantly different." (PMID 35295780, 2022). "However, it is unknown what is the difference between reactive and endogenous depression in terms of NLRP3 expression." (PMID 35295780, 2022). "Antidepressants decreased IL-1β and IL-18 levels in serum and suppressed NLRP3 expression in MDD patients and mice with stress-induced depression." (PMID 36558541, 2022). "Therefore, Xiaoyaosan may alleviate anxiety and depression by modulating the gut microbiota, correcting excessive LPS release, and inhibiting the immoderate activation of the NLRP3 inflammasome in the colon." (PMID 33935710, 2021). "Moreover, we used NLRP3 KO mice to determine the role NLRP3 played in depression." (PMID 34103482, 2021). "Moreover, it has recently been reported that BHB might exert its anti‐inflammatory effects in a rodent depression and post‐traumatic stress disorder model via NLRP3 inflammasome modulation." (PMID 33609086, 2021). "The expression levels of NLRP3 inflammasome mRNA and IL-1β are significantly increased in the brains of depressed mice induced by lipopolysaccharide (LPS), suggesting that IL-1β and NLRP3 inflammasome are the mediators of inflammation between stress and depression." (PMID 32166013, 2020). "Therefore, the role of P2X7 receptor-mediated NLRP3–IL-1β pathway in depression must be clarified." (PMID 32166013, 2020). "Therefore, NLRP3 plays an important role in regulating the onset and development of depression." (PMID 32166013, 2020). "Thus, NLRP3 inflammasome is an inflammatory target of depression." (PMID 32328132, 2020). "However, whether the NLRP3 inflammasome is activated in hippocampal microglia during chronic restraint stress and depression remains unclear." (PMID 31555091, 2019). "Therefore, microglia and the NLRP3 inflammasome may have potential as drug targets for the treatment of depression." (PMID 31555091, 2019). "Moreover, various novel studies implied that the NLRP3 inflammasome is involved in stress-induced depression and, therefore, may be a potential target for the treatment of depression." (PMID 29343269, 2018). "Furthermore, the depression rat model indicated that the CUMS-induced MAPK pathway could be regulated by NLRP3 inflammasome by activating the NF-κB protein complex." (PMID 30618863, 2018). "Consequently, targeting on the NLRP3 inflammasome might serve as a potential therapy in the alleviation of depression." (PMID 30233319, 2018). "Therefore, inhibiting hippocampal NLRP3 inflammasome activation may be a potential therapeutic approach to the treatment of AD, depression, and anxiety." (PMID 29495433, 2018).